BRD2 (bromodomain containing 2)
Diseases named in the same sentence as BRD2 in open-access papers (continued):
Sharing a sentence is not in itself a finding about the gene and the disease.
gastric cancer (4 papers, 2020 to 2025). A primary or metastatic malignant neoplasm involving the stomach. "This is also the first report to show that BRD2 could regulate Caspase-8 to induce PANoptosis in gastric cancer." (PMID 39744419, 2025). "Organoid culture assay of gastric cancer cells also demonstrated that after knockdown of BRD2, the growth of GC organoid was inhibited significantly compared to 5-FU treated alone or knockdown of BRD2 alone, confirming sensitivity of 5-FU changing in vitro." (PMID 39744419, 2025). "In our study, we identified BRD2 as a key regulator of chemotherapy in HP-positive gastric cancer." (PMID 39744419, 2025). "ARV-825 induced degradation of BRD4, BRD2, BRD3, c-MYC, and polo-like kinase 1 (PLK1) proteins in four gastric cancer cell lines." (PMID 34733788, 2021). "It is the first time to report that BRD2 could promote the nucleus import of FOXO4, which again extended the functions of BRD2, making BRD2 again the potential therapeutic target of future gastric cancer chemotherapy." (PMID 39744419, 2025). "Thus, BRD2 disrupts the homeostasis of the FLP/Caspase-8 homeostasis and regulates apoptosis and apoptosis in HP-positive gastric cancer cells." (PMID 39744419, 2025). "BRD4, BRD2, and BRD3 were abundantly expressed in MGC803, HGC27, AGS, SGC7901, BGC823, and SNU-216 cells, implying that the BET proteins were diffusely expressed in gastric cancer cells." (PMID 34733788, 2021).
lung cancer (4 papers, 2019 to 2025). A malignant neoplasm involving the lung. "In this study, pharmacologic inhibition and genetic silence of BRD2/BRD4 obviously downregulated GPX8 expression and prevented migration both in lung cancer cells and CAF." (PMID 35978854, 2022). "As BRD2 and BRD4 were validated as the upstream regulators of GPX8, inhibition of GPX8 by bromodomain and extra‐terminal (BET) inhibitors may serve as a novel therapeutic potential for lung cancer metastasis." (PMID 35978854, 2022). "Thus, BRD2 and BRD4 could regulate GPX8 expression and BET inhibitors may serve as a treatment strategy for GPX8‐driven lung cancer metastasis." (PMID 35978854, 2022). "Nonetheless, a recent study utilizing a CRISPR screen found BRD2, rather than BRD3 or BRD4, promotes EMT in lung cancer models." (PMID 37461511, 2023).
B-cell lymphoma (3 papers, 2008 to 2025). "Further, a pull-down assay of lysates from BCP-1 cells, a KSHV-infected B-cell lymphoma cell line, with an anti-BRD2 antibody results in the immunoprecipitation of both BRD2 and LANA, indicating interaction between BRD2 and LANA in vivo." (PMID 27827996, 2016). "First, constitutive lymphoid expression of Brd2 results in B cell lymphoma characterized in part by transactivation of proliferation-promoting genes, including E2F-regulated cell cycle genes." (PMID 18402692, 2008).
colon cancer (3 papers, 2019 to 2023). "BRD2 may have both activation and inhibition functions, which was also confirmed by the bidirectional effect of JQ1, an inhibitor of the BRD4/BRD2 target, in colon cancer." (PMID 31523195, 2019). "Extending our prior immunoblotting work in cell-based assays, screening of SW48, CaCo2, HT29, LoVo and SW620 human colon cancer cell lines revealed moderate to high constitutive expression of ACE2, BRD2 and BRD4 proteins compared with CCD841 normal colonic epithelial cells." (PMID 36801948, 2023). "Among the upstream regulators (TFs, kinases, and MMTRs) of the DEGs, the expression of STAT3, RPS6KA5, IKBKE, ERBB2, MTOR, and NFKB1 had a positive correlation with OS in colon cancer, while the expression of CDK1, CDK5, and BRD2 had a negative correlation with OS in colon cancer." (PMID 31186640, 2019).
medulloblastoma (3 papers, 2013 to 2023). A malignant, invasive embryonal neoplasm arising from the cerebellum. "Of note, BRD2 levels were increased in medulloblastoma cell lines when treated with JQ1." (PMID 37393376, 2023). "In medulloblastoma spheroid cells, however, we did find a profound JQ1-induced increase of BRD2 protein." (PMID 37393376, 2023). "Taken together, BRD2, BRD3 and BRD4 are expressed in primary medulloblastomas." (PMID 24231268, 2013). "Since siRNA-mediated depletion of the BRD2 BET protein has been described to reduce transcription of cyclin D1 in human cells, we investigated the result of siRNA-mediated BRD4 knockdown on CCND1 regulation in medulloblastoma cells." (PMID 24231268, 2013). "The RNA-seq results from Fsmo;hGFAP-Cre medulloblastomas showed significant downregulation of histone acetyltransferases (HAT: Hat1 and Kat2a/GCN5), the histone deacetylase (HDAC) Hdac1, and the histone acetylation reader Brd2 between vehicle- and LDE-treated samples." (PMID 36688010, 2022). "BRD2 and BRD4 were both expressed in all primary medulloblastomas in this medulloblastoma cohort, however, expression was not significantly higher than in cerebellar tissue." (PMID 24231268, 2013).
multiple myeloma (3 papers, 2015 to 2025). "Selective inhibition has differential effects: BRD4 inhibition alone suppresses tumor growth in multiple myeloma, AML, and solid tumors, whereas dual BRD2/BRD4 inhibition is often required in resistant models." (PMID 41583469, 2025).
neuroblastoma (3 papers, 2007 to 2022). Neuroblastoma (NB) is the most common solid, extracranial childhood tumor. "It precisely targets BRD4 proteins, induces the degradation of BRD2 and BRD3, and has a strong antitumor effect on neuroblastoma." (PMID 36438198, 2022). "All the cell lines tested expressed BRD2, BRD3 and BRD4 at least two times more than normal mesenchymal stem cells (MSCs), except the SK-N-MC cells, potentially because of their neuroblastoma origin." (PMID 27006472, 2016).
ovarian carcinoma (3 papers, 2020 to 2022). A malignant neoplasm originating from the surface ovarian epithelium. "BRD2 mRNA expression exhibited significantly better association with OS among all the ovarian cancer patients together with serous histological subgroup, HR =0.81 (0.71 - 0.92), P=0.0012, HR =0.81 (0.69 - 0.96), P=0.012." (PMID 35371325, 2022). "Our results showed that the protein level of BRD2, BRD3, BRD4, and BRDT in ovarian cancer cell lines was all subsided associated to the normal breast cell (P < 0.05)." (PMID 35371325, 2022). "Concerning clinical stages, BRD2 and BRD3 in advanced stage (III+IV), and BRDT in all clinical stages (I+II, III+IV) were associated with the better OS in ovarian cancer patients, although high BRD4 mRNA level showed worse OS in early-stage (I+II) patients with ovarian cancer." (PMID 35371325, 2022). "In addition, subgroup survival analysis of ovarian cancer patients with various treatment strategies illustrated that overexpression of BRD2 mRNA was significantly correlated with an improved OS for patients treated with Platin-based chemotherapy compared with low expression." (PMID 35371325, 2022). "We observed that high levels of BRD2, BRD3, and BRDT indicated a better prognosis, whereas BRD4 predicted poor clinical outcomes in patients with ovarian carcinoma." (PMID 35371325, 2022). "High expression of BRD2 mRNA in grade II and grade III was correlated to a better OS in patients with ovarian cancer." (PMID 35371325, 2022). "The BRD2, BRD3, and BRDT mRNA expression in the human ovarian cancer cell lines were all considerably downregulated in relationship with those in a normal ovarian cell line (P < 0.05)." (PMID 35371325, 2022). "First, we did not investigate the prognostic functions of four BET members (BRD2,3,4, and BRDT) in ovarian cancer." (PMID 35371325, 2022). "A recent study reported that BET proteins regulated RAD51 in ovarian cancer cells, and we showed that knockdown of each BET family member (BRD2, BRD3, and BRD4) in DMS273 cells led to downregulation of Rad51 expression." (PMID 33134168, 2020). "However, high BRD2 mRNA expression in grade I and BRD4 mRNA in grade III showed significantly poor OS in patients with ovarian cancer." (PMID 35371325, 2022). "The expression of BRD4 is significantly higher in clinical ovarian cancer tissues than in non-malignant control tissues, whereas the levels of BRD2 and BRD3 do not significantly vary between malignant and non-malignant tissues." (PMID 34540687, 2021).
ovarian clear cell cancer (3 papers, 2018 to 2022). An invasive malignant neoplasm that arises from the ovary and is characterized by a predominance of clear and hobnail malignant epithelial cells. "Using the largest OCCC cell line panel established to date, we show here that BRD2 inhibition is predominantly lethal in ARID1A mutated ovarian clear cell cancer cells." (PMID 29760405, 2018). "For example, the BRD2 inhibitor, JQ1, can suppress ARID1A-deficient ovarian clear cell cancer cells because BRD2 inhibition decreases ARID1B transcription." (PMID 36371186, 2022). "Importantly, small molecule inhibitors of the BET (bromodomain and extra terminal domain) family of proteins, to which BRD2 belongs, specifically inhibit proliferation of ARID1A mutated cell lines, both in vitro and in ovarian clear cell cancer xenografts and patient-derived xenograft models." (PMID 29760405, 2018).
Parkinson disease (3 papers, 2021 to 2024). A progressive degenerative disorder of the central nervous system characterized by loss of dopamine producing neurons in the substantia nigra and the presence of Lewy bodies in the substantia nigra and locus coeruleus. "BANF1, PCGF5, WDR5, RYBP and BRD2 are related to the immune process of Parkinson’s disease and can predict the occurrence of Parkinson’s disease, which is expected to become a new target for the diagnosis and treatment of Parkinson’s disease." (PMID 36813848, 2023).
pulmonary fibrosis (3 papers, 2019 to 2022). Chronic progressive interstitial lung disorder characterized by the replacement of the lung tissue by connective tissue, leading to progressive dyspnea, respiratory failure, or right heart failure. "Moreover, the dual advantage of using SF2523 is that since BRD2/BRD4 induces pro‐fibrotic genes and promotes lung tissue fibrosis, which is majorly seen in COVID‐19 patients; therefore, inhibition of BRD2/BRD4 may prevent lung fibrosis and promote fast recovery as well." (PMID 35942238, 2022). "Importantly, our finding that Brd3 and Brd4, but not Brd2, are involved in NOX4 regulation by TGF-β suggests that a degree of selectivity may be possible when considering BET inhibitors as possible therapeutic agents in pulmonary fibrosis." (PMID 31119153, 2019).
rheumatoid arthritis (3 papers, 2016 to 2023). A chronic, systemic autoimmune disorder characterized by inflammation in the synovial membranes and articular surfaces. "BRD2 directly regulates multiple TH17-associated cytokines, including IL17, IL21, and GMCSF32, and altered TH17 cells mediate autoimmune conditions, including multiple sclerosis, psoriasis, rheumatoid arthritis, and CD32." (PMID 28008999, 2016). "We show that both BRD2 and BRD4 control inflammatory cytokine production in NK cells isolated from healthy volunteers and from rheumatoid arthritis patients." (PMID 33717143, 2021).
viral infection (3 papers, 2020 to 2024). "Currently, accumulating studies have also revealed that the BRD2, BRD3 and BRD4 proteins participate in the host immune response against virus infection." (PMID 32962745, 2020).
acute leukemia (2 papers, 2015 to 2023). A clonal (malignant) hematopoietic disorder with an acute onset, affecting the bone marrow and the peripheral blood. "Degrader 15 catalyzed the selective removal of BRD4 and BRD2, and effectively inhibited cell growth of human acute leukemia, breast cancer and non-small-cell lung cancer, with the GI50 values in the nanomolar range." (PMID 36986673, 2023). "ZBC260 induced degradation of BRD2, BRD3 and BRD4 at concentrations as low as 0.1–0.3 nM and downregulated c-Myc at 0.1 nM in the acute leukemia cell line RS4;11." (PMID 36986673, 2023).
fragile X syndrome (2 papers, 2021 to 2024). A genetic syndrome caused by mutations in the FMR1 gene which is responsible for the expression of the fragile X mental retardation 1 protein. "In a mouse model of fragile X syndrome (FXS), BRD2/3 and BRD4 showed oppositely altered expression and chromatin binding, correlating with transcriptional dysregulation." (PMID 34138732, 2021). "For example, CBP/p300 depletion in a fragile X syndrome (FXS) mouse model resulted in decreased binding of BRD4 but not BRD2/3 to promoters and enhancers of regulatory regions and rescued behavioral impairments." (PMID 38914477, 2024).
gastric tumors (2 papers, 2021 to 2024). "A new report has shown that BRD2 is a direct target of MIR143–3p and increased expression level of BRD2 in gastric tumors was related with shorter survival times for GC patients." (PMID 34079823, 2021).
liver cancer (2 papers, 2024 to 2025). An epithelial or non-epithelial malignant neoplasm that arises from the liver. "Meanwhile, short hairpin RNA (shRNA)-mediated knockdown of BRD2 and BRD4 in the liver cancer cell line Huh7 significantly slowed down cell proliferation, suggesting that both BRD2 and BRD4 were important for liver cancer cell growth." (PMID 39872506, 2024). "We find that both BRD2 and BRD4 but not BRD3 are required for liver cancer cell growth, and even transient BET suppression using pan-BETis (JQ-1 and ABBV075) is sufficient to impede cell proliferation and xenograft tumor growth." (PMID 39872506, 2024).
osteosarcoma (2 papers, 2019 to 2020). A usually aggressive malignant bone-forming mesenchymal neoplasm, predominantly affecting adolescents and young adults. "Our screens indicated that BRD2 may be a potential target for osteosarcoma, which deserves further investigation in the future." (PMID 32944406, 2020).
pancreatic ductal adenocarcinoma (2 papers, 2017 to 2025). An infiltrating adenocarcinoma that arises from the epithelial cells of the pancreas. "•Epigenetic Regulation: HYAL1 expression is directly regulated by epigenetic factors such as BRD2, revealing a novel layer of transcriptional control in cancers like pancreatic ductal adenocarcinoma." (PMID 41421148, 2025). "To validate the screening results, we knocked down the genes encoding BRD2, BRD3, or BRD4 in human pancreatic ductal adenocarcinoma KP-4 cells and determined their effects on autophagy by monitoring the levels of the lipidated form of LC3 (LC3II)—a marker of autophagosome formation/accumulation." (PMID 28525743, 2017).
photosensitive epilepsy (2 papers, 2018 to 2023). An epilepsy characterized by seizures triggered by visual stimuli that form patterns in space or time, such as flashing lights. "The human BRD2 gene, family II of bromodomain proteins, has been associated with myoclonic epilepsy and photosensitive epilepsy with electroencephalographic abnormalities." (PMID 36514184, 2023).
psoriasis (2 papers, 2016 to 2024). An autoimmune condition characterized by red, well-delineated plaques with silvery scales that are usually on the extensor surfaces and scalp. "Furthermore, this study marks the initial identification of several proteins—MAPRE1, SWAP70, VPS26A, BRD2, and B3GNT2—as potentially contributing factors in the pathogenesis of psoriasis." (PMID 39883516, 2024).
renal fibrosis (2 papers, 2016 to 2021). A final common manifestation of a wide variety of chronic kidney diseases characterized by glomerulosclerosis and tubulointerstitial fibrosis. "Coincident with Brd2 and Brd4 repression, I-BET151 improved renal function and attenuated renal fibrosis." (PMID 33664670, 2021).
triple-negative breast carcinoma (2 papers, 2020 to 2021). An invasive breast carcinoma which is negative for expression of estrogen receptor (ER), progesterone receptor (PR), and human epidermal growth factor receptor 2 (HER2). "The BRD4 degrader MZ1 potently and rapidly induces preferential removal of BRD4 over BRD2 and BRD3, and has shown high efficacy in ovarian and triple-negative breast cancer in vivo." (PMID 33958721, 2021). "It is also known that BRD2 promotes EMT, while BRD3 and BRD4 negatively regulate this process in triple-negative breast cancer." (PMID 32961679, 2020).
acute myeloid leukemia (1 paper, 2025). Acute myeloid leukemia (AML) is a group of neoplasms arising from precursor cells committed to the myeloid cell-line differentiation. "It induces CRBN-dependent degradation of BET family proteins, including BRD2, BRD3, and BRD4, in human acute myeloid leukemia (AML) cells with a DC50 of 100 nM." (PMID 40507351, 2025).
Adult onset (1 paper, 2023). Onset of disease manifestations in adulthood, defined here as at the age of 16 years or later. "In conclusion, this study provides evidence that rare and low-frequency coding variants associated with adult-onset MS (PRF1) and within the MHC region (BRD2 and AGER) are associated with POMS susceptibility." (PMID 36755464, 2023). "These included variants within PRF1, a gene that was previously identified as associated with adult-onset MS, and two genes in the MHC region (BRD2 and AGER)." (PMID 36755464, 2023).
Alzheimer disease (1 paper, 2017). A progressive, neurodegenerative disease characterized by loss of function and death of nerve cells in several areas of the brain leading to loss of cognitive function such as memory and language. "Here we tested the effect of JQ1—a small-molecule inhibitor of the chromatin readers BRD2, BRD3, BRD4 and BRDT—on brain function and show that JQ1 is able to enhance cognitive performance and long-term potentiation in wild-type animals and in a mouse model for Alzheimer’s disease." (PMID 28949335, 2017).
asthenospermia (1 paper, 2022). "Among the significantly upregulated piRNAs, piR-26951 was predicted to target transcripts encoding flagella-associated protein 45 (CFAP45) and bromodomain-containing protein 2 (BRD2), both found to be differentially expressed in the sperm of patients with asthenospermia." (PMID 36555356, 2022).
autoimmune disease (1 paper, 2024). A disorder resulting from loss of function or tissue destruction of an organ or multiple organs, arising from humoral or cellular immune responses of the individual to their own tissue constituents. "Then, we performed mediation analyses, which showed that POR, HSPA1B, SHANK3, and BRD2 might exert mediating effects from air pollutants to increased risk of autoimmune diseases." (PMID 38685026, 2024). "Furthermore, intermediate analyses revealed that air pollutants increased the risk of autoimmune diseases by modulating the expression of POR, HSPA1B, SHANK3, and BRD2." (PMID 38685026, 2024). "Two-step MR revealed that POR, HSPA1B, and BRD2 might mediate from air pollutants to autoimmune diseases." (PMID 38685026, 2024).
bladder carcinoma (1 paper, 2019). "Gaballah identified candidate genes: PURA, SRPK2, TRAK1, BRD2, and UPF3 in progression and invasiveness of bladder carcinoma based on DEGs acquired by comparing invasive and noninvasive samples by Limma R packages in 2016." (PMID 30723390, 2019).
breast tumor (1 paper, 2022). "Despite this, BRD2, BRD3, and BRDT expression were discovered to be low in normal breast tissues, while it was shown to be high and medium in the cytoplasmic and membranous parts of breast tumor tissues, respectively." (PMID 35371325, 2022).
Burkitt lymphoma (1 paper, 2015). A rare form of malignant mature B-cell non-Hodgkin lymphoma. "Both JQ1 and PFI-1, another highly selective inhibitor of BRD4 and BRD2, also displayed significant antitumor activities in vivo in xenograft models of DLBCL, Burkitt’s lymphoma or acute myeloid leukemia and thereby improved survival of engrafted mice." (PMID 26654227, 2015).